NFKB2 (nuclear factor kappa B subunit 2)
Diseases named in the same sentence as NFKB2 in open-access papers (continued):
Sharing a sentence is not in itself a finding about the gene and the disease.
tumor (39 papers, 2008 to 2025). "Other notable findings in this tumour included missense variants in NFKB2, NF2 and USP6." (PMID 37435187, 2021). "Integration of NF-κB+ patient expression data showed that 35% of genes downregulated in the NFKB2 KD KMS-11 transcriptional profile were overexpressed in NF-κB+ primary MM tumours." (PMID 38514625, 2024). "Based on the analysis of a small genetic sample of 10 paired CRC/adjacent non‐tumor samples, NFKB2 was among the top‐ranked deregulated genes and its expression was significantly upregulated." (PMID 38660687, 2024). "The results revealed that Nfkb2 significantly promoted subcutaneous tumor formation in MC38‐C57BL/6 mouse models and CT26‐BALB/c mouse models." (PMID 38660687, 2024). "This indicates that NFKB2 suppresses T‐cell infiltration and impairs T‐cell effector functions in the tumor microenvironment." (PMID 38660687, 2024). "In further spatial localization analysis, we observed that there is an increased expression of STAT2 and PD‐L1 in tumor tissues overexpressing Nfkb2 as well as in CRC samples with high NFKB2 expression." (PMID 38660687, 2024). "NFKB2 has frequent mutations in cancers, and it is related with abnormal TNF signal transduction and tumor diseases." (PMID 36323529, 2023). "Our multivariate survival analyses adjusted for WHO grade and extent of resection, indicated the independent prognostic significance of high PD-L1 and NFKB2 co-expression to predict tumor progression (p = 0.002, HR = 1.57,CI(95%) = 1.117–2.11)." (PMID 32839486, 2020). "The core dynamic DEGs (Mnda, Cyp1b1, Comp, Phex, Mmp3, Tnfrsf1b, Fbln5, and Nfkb2) had been reported to be closely related to the development and metastasis in tumor and cancer progress." (PMID 33042984, 2020). "NFKB2 played an important role in promoting tumor growth through CD8+ T‐cell exhaustion." (PMID 38660687, 2024). "We further examined the impact of NFKB2 on immune cells within the tumor microenvironment." (PMID 38660687, 2024). "Moreover, high NFKB2 mRNA levels were correlated with bigger tumor size, poorer differentiation grade, and worse tumor node metastasis (TNM) stage." (PMID 38660687, 2024). "As crosstalk between tumor cells and the immune system is generally considered a pivotal factor in CRC development, we hypothesized that the murine immune system may contribute to the tumor‐promoting function of NFKB2 in syngeneic mouse models." (PMID 38660687, 2024). "Similarly, immune/inflammation-related TFs, such as NFKB2, STAT1, and RELA, and FOXO3, showed high activity in CXCL10+MEL and TMSB4X+MEL subclusters, which underlies the immunomodulatory phenotype of tumor cells." (PMID 38065972, 2023). "At this time point, NFKB2 and RelA genes were strongly reduced in both healthy and tumor conditions (NFKB2 in h3D vs. 2D p = 0.023; t3D vs. 2D p = 0.014; RelA in h3D vs. 2D p = 0.020; t3D vs. 2D p = 0.006), while the t3D samples also downregulated NFKB1 (p < 0.001)." (PMID 34070750, 2021). "Moreover, Nfkb2 was shown to be frequently mutated in cancers and aberrant TNF signaling has been implicated in neoplastic diseases." (PMID 31134075, 2019). "Compared with wild‐type, Nfkb2−/− mice developed fewer, smaller tumours." (PMID 25727407, 2015). "However, NFkB2 may cooperate with Dek-mediated inhibition of canonical NFkB signaling to control cytokine and chemokine gene expression that drive tumor progression through effects on the microenvironment and the anti-tumor immune response." (PMID 32708944, 2020). "Furthermore, our exploration of the transcriptomic differences between PanIN-associated immature and mature TLSs (found outside the tumor margin) showed a correlation with B cell development transcription factors and protein expression, except NFKB2 activity, which was not included in the IMC panel." (PMID 40569674, 2025).
tumor (continued). "Further, expression levels of TF regulators in the NF-κB family (NFKB1, NFKB2, RELA, RELB) were highest in TS3 cluster, reinforcing the notion that NF-κB pathway activation within the tumor epithelium drives TS3." (PMID 39289380, 2024). "Our findings demonstrated a significant reduction in the expression of CD4, CD8, and granzyme B (GZMB) in Nfkb2‐overexpressing MC38 tumor tissues and CRC tumor samples with high NFKB2 expression." (PMID 38660687, 2024). "We identified ginsenoside Rg5 as an inhibitor of NFKB2 activity, which resulted in increased CD8+ T‐cell populations, reduced tumor size, and inhibited PD‐L1 expression." (PMID 38660687, 2024). "Our study found that NFKB2 is overexpressed in CRC and CRC‐hepatic metastasis samples, promoting tumor formation and metastasis in CRC models." (PMID 38660687, 2024). "NFKB2 was frequently overexpressed in EBV+ NPC cells, instead of EBV- tumor cells, NPE cells, stromal cells, and immune cells in the TME, and has been previously shown to promote tumor growth and survival." (PMID 37024479, 2023). "We further confirmed the p52-driven tumorigenic effects in vivo whereby TWEAK overexpression significantly increased the growth of U-87 MG tumour xenografts, but this was reduced by CRISPR/Cas9-mediated knockdown of NFKB2 or ETS1." (PMID 37087499, 2023). "In the protein level, the gene expression of HSP90AA1, NFKB2, PTK2 was upregulated in tumor tissues, and CLU, JAK2, MAP3K5, and S100B were downregulated in the normal tissues." (PMID 36323529, 2023). "Among the down-regulated genes, GLI1 and some other tumor progression related genes were discovered, for example, MMP1, MMP9, NFKB2, TGFA, and EGFR." (PMID 33637972, 2021). "We observed high expression of NFKB2 and CA9 positivity significantly predicted the tumor recurrence in our cohort; p = 0.0004 and p = 0.02, respectably." (PMID 32839486, 2020). "We then used Kaplan Meier survival analysis of patients’ RFS and found that PD-L1 co-expression with NFKB2 (p < 0.001) and also with CA9 expression; a hypoxic biomarker significantly predicted tumor progression in our cohort (p = 0.001)." (PMID 32839486, 2020). "The present study revealed that MC38 subcutaneous tumor growth was significantly reduced under NFKB2 inhibition by Rg5 in immunocompetent but not immune‐deficient mice." (PMID 38660687, 2024). "We also evaluated the promoting effects of NFKB2 on cell metastasis by establishing an orthotropic transplantation model and found that NFKB2 significantly promote hepatic metastasis in MC38 and CT26 CRC tumor models." (PMID 38660687, 2024). "In GC, NFKB1, NFKB2, REL, RELA, and RELB were significantly upregulated in tumor tissues." (PMID 35036435, 2022). "As expected, non-transgenic Nfkb2-/- littermates showed no signs of tumour development throughout their lifespan (data not shown)." (PMID 20598117, 2010). "Consequently, NFKB2 overexpression should have shown its ability on the tumorigenesis of HT‐29 cells in vivo, but surprisingly, there was no obvious effects that NFKB2 promote the tumor growth of HT‐29 xenografts in nude mouse models." (PMID 38660687, 2024).
cancer (37 papers, 2010 to 2025). A tumor composed of atypical neoplastic, often pleomorphic cells that invade other tissues. "Patients in the low-risk group were enriched in expression genes of cancer-suppressing inflammation such as NFKB2 and CCR5." (PMID 35832540, 2022). "Our study reveals that Rg5 exerts anti‐cancer effects by reducing PD‐L1 expression through modulating the stability of the NFKB2/STAT2 protein complex." (PMID 38660687, 2024). "Most of the genes in the subnetworks were inflammatory cytokines and participated in TNF signaling pathways and pathways in cancer, such as Ccl2, Ccl20, Csf1, Cx3cl1, Cxcl1, Cxcl3, Il6, Birc3, Map3k8, Nos2, Nfkb2, Tnfrsf1b, and Vcam1." (PMID 33042984, 2020). "We focused on the genes TNFRSF12A, CD44 and NFKB2 in more detail given their role in the multiple cellular pathways and cancer and the high scoring of the corresponding switching events." (PMID 30857150, 2019). "Remarkably, USP22 knockout had pronounced effects on expression of these important cancer-associated gene sets such as c-Myc, E2F, and selected genes including ALDH1A3, CCNE1/G1, E2F6, HOXA1, MMP9, NFKB2, TP63, TPM4, SET7/9 were validated by qRT–PCR." (PMID 31842906, 2019). "Elevated expression levels of NFKB2 and the activation of the alternative pathway of NF‐κB have been confirmed in non‐small cell lung cancer, breast cancer, prostate tumors, and several cancer cell lines." (PMID 38660687, 2024). "Wnt/β-catenin signaling and expression patterns of important genes in cancer cell growth and survival, which were further suggested to play a role in three-dimensional aggregation, such as NFKB2, VEGFA, CTGF, CAV1, BCL2(L1), or SNAI1, were clearly affected by DEX." (PMID 32033410, 2020). "Long-term F. nucleatum stimulation may increase the risk of cell carcinogenesis by altering many inflammation- and cancer-related genes and pathways, such as Mnda, Cyp1b1, Comp, Phex, Mmp3, Tnfrsf1b, Fbln5, and Nfkb2." (PMID 33042984, 2020). "Furthermore, the networks related to cell cycle, cancer and nervous system development and function showed that several genes such as Nfkb2, NFκBia, BRCA1, Vegf, Jag2, Notch1, EGR1, FoxS1 and collagen type I were regulated by TNF." (PMID 20967264, 2010). "On this basis, it has been suggested that aberrant activation of NFKB2 (p52) may lead to cancer." (PMID 36555871, 2022). "Copy number amplification of the 10q24.32 locus in patients with advanced CRC leads to increased NFKB2 expression and its binding with STAT2, resulting in the activation of the PD‐L1/PD‐1 axis and immune escape by cancer cells." (PMID 38660687, 2024). "NFKB2 gene is part of the NFKB pathway family genes, which is an important regulator in immune reactivity in various types of cancer including GC." (PMID 33843442, 2021). "In the comprehensive prognostic signature, genes such as NFKB2, DLK1, KANK1, play important roles in cancer biology." (PMID 33193606, 2020). "Upregulated genes included members of the tumor necrosis factor superfamily (TNFRSF9, TNFRSF11B, and TNFSF8), ABC transporters (ABCB1 and ABCG2), and nuclear factor (NF)-κB-related genes (NFKB2 and RELB), all of which induce stemness in cancer cells." (PMID 28423353, 2017). "As shown, the expression of NFKB1, NFKB2, REL, RELA, and RELB varied in different cancer types." (PMID 35036435, 2022). "Just as in NFKB1 expression, NFKB2 mRNA was found as the highest levels in PC, but the observed upregulation between normal and cancer samples was not as high (ca. 3.5 times higher than in control and normal foreskin)." (PMID 36555871, 2022).
cancer (continued). "UBE2D2 and NFKB2 may go through TLR4 to influence IRF1 to destroy the immune system and promote the occurrence and development of cancer." (PMID 34445498, 2021). "Protein Bcl-3, the expression of which is upregulated in both cancer cell lines, may bind to NFKB1 and NFKB2 homodimers and form complexes that function as transcriptional activators." (PMID 24037645, 2013).
infection (32 papers, 2006 to 2025). The state of being infected such as from the introduction of a foreign agent such as serum, vaccine, antigenic substance or organism. "Clinical features, infection profile, and treatment of patients with NFKB2 mutations." (PMID 30941118, 2019). "Finally, bacterial colitis induced in Nfkb2−/− mice resulted in significant body weight loss and onset of mortality as early as day10 post-infection." (PMID 25905673, 2015). "RT-qPCR analysis confirmed the significant upregulation of Tnf, Malt1, Nfkb1, and Nfkb2 following infection, consistent with transcriptomic findings." (PMID 40248690, 2025). "For instance, L. amazonensis interferes with NF-κB TF function through downregulation of RELA, NFKB1, and NFKB2 during early infection in BMDM." (PMID 39639867, 2024). "Along the course of infection, there was a reduction in the expression of M1 markers like Nos2, Cd40,Cd86, Tnfa, Nfkb2, Il6 and a corresponding increase in the expression of the M2 markers such as Arg1, Ccl17, Cd206, IL4ra with an exception of Tgfb." (PMID 39693143, 2024). "By contrast, during infection transcription of nfkb-2 was up-regulated to a similar extent in the blood, irrespective of diet, as well as in the lungs of Zn-restricted mice." (PMID 31437249, 2019). "Our inability to rescue the infection-related mortality in Nfkb2−/− mice using WT hematopoietic cells indicated that the protective function of Nfkb2 lies within stromal cells." (PMID 25905673, 2015). "WT bone marrow cells in Nfkb2−/− recipients were unable to prevent the infection-related colon pathology, reductions in the body weight and morality." (PMID 25905673, 2015). "Notably, our study observed morphological changes in macrophages post-infection, along with upregulation of key NF-κB pathway genes (Nfkb1, Nfkb2, Tnf, and Malt1), further establishing F. nucleatum’s contribution to an immunosuppressive TME in CRC." (PMID 40248690, 2025). "Notably, NFKB1 and NFKB2, two central activators of genes involved in inflammation and immune function, were significantly upregulated at 3 h after F. nucleatum-infection and showed sustained activation at 6 h and 12 h." (PMID 36754953, 2023). "While WT mice efficiently eliminated infections, increased fecal excretion of bacteria at day10 post-infection in Nfkb2−/− mice indicated an inadequacy in limiting local infection, thereby, correlating with the observed defects in the early innate inflammatory response in this knockout." (PMID 25905673, 2015). "The non-canonical route is activated in HRSV-infected cells, and we have shown that genes involved in this pathway, including NFKB2, RELB, and NIK, are upregulated at later times post-infection." (PMID 32102364, 2020). "The genes, Ccl2, Ccl20, Csf1, Cx3cl1, Cxcl1, Cxcl3, Il6, Birc3, Map3k8, Nos2, Nfkb2, Tnfrsf1b, and Vcam1, played core roles in a PPI network, and interacted closely with other ones in the infection." (PMID 33042984, 2020). "Our systems biology analysis revealed that 13 hub genes, including the classical inflammatory genes (IL6, NFKB2, JUN, IL-1β, and CXCL2) which regulate retinal innate responses during infection." (PMID 26865111, 2016). "The systems biology analysis identified multiple immune system and inflammation molecules (e.g., STAT3, STAT1, CEBPB, JUN, IGF1, SPP1, NFKB2, IL-1β, and CSF1) as master regulators that are activated upon infection." (PMID 26865111, 2016). "Infection by genetically diverse clinical strains of M. tuberculosis revealed an upregulation of NFKB1 and NFKB2 transcriptional factors that lead to the transcription of IL1β, while IL18 was slightly down-regulated at 48 h infection by East-Asian and Euro-American lineages." (PMID 34502407, 2021). "Indeed, aligned with prior reports that O. tsutsugamushi stimulates the NF-κB response initially following invasion but then actively represses it as infection proceeds, NFKB1 and NFKB2 were among several genes upregulated at 4 h but downregulated at 48 h." (PMID 34340535, 2021).
infection (continued). "The NFKB2 and NFKBIA proteins are highly pleotropic but are best known for their involvement in the NFKB Pathway, a well-characterized pathway initiated during host infection." (PMID 33148169, 2020). "Dilated cystic glands also developed in WT and c-Rel−/− mice following infection, but were absent from both infected and uninfected Nfkb2−/− mice at this time point." (PMID 23975431, 2013). "To reach this goal, we examined a dataset of DANCR knockdown (KD) in neuron progenitor cells and found downregulation of cytokines and the non-canonical pathway NFkB (IL-6 and NFKB2, p<0.05, FDR), indicating increased susceptibility to infection in differentiated neurons." (PMID 33163005, 2020).
immunodeficiency (8 papers, 2014 to 2024). Failure of the immune system to protect the body adequately from infection, due to the absence or insufficiency of some component process or substance. "They reported the comprehensive immune evaluation of patient 4 and provide evidence that aberrant NFKB2 signaling not only causes humoral immune deficiency, but also interferes with the TCR-mediated proliferation of T cells." (PMID 26284228, 2015). "In addition, genes related to immune diseases (e.g., BID, SMARCD3, ATP6V1E1, NFKB2), energy metabolism (e.g., HAO1, NDUFA7, CERS4, MTHFD1), and other factors were also screened." (PMID 38750582, 2024).
gastrointestinal disease (1 paper, 2022). A disease that occurs in the gastrointestinal system, excluding the hepatobiliary system. "In many experimental models of gastrointestinal diseases, deficiency of the Nfkb2 gene presents a distinct phenotype compared with phenotypes observed following deficiency of other NF-κB subunits, such as Nfkb1 or cRel." (PMID 35916405, 2022).
genetic disorder (1 paper, 2022). "One patient with NFKB2 deficiency was treated because of her progressive disease and of critical COVID-19 previously reported in young patients with this genetic disorder." (PMID 34893946, 2022).
heart disease (1 paper, 2022). "Among these transcription factors, Ikbkb, Nfkb1 and Nfkb2 have been used as drug targets for the treatment of heart disease." (PMID 35811717, 2022).
vascular disorder (1 paper, 2017). A general term used to describe any disease affecting blood vessels]. "Complexes such as Bcl3/NF-kappaB2 complex (governed by BCL3 and NFKB2), vacuolar lumen (governed by CLN5), IPAF inflammasome complex (CASP1, CASP4, NLRC4) help to understand the involvement of inflammation and vascular disorder in AD." (PMID 28199395, 2017).
NFKB2 also shares sentences with these, for which no sentence is quoted: asthma (4 papers); adrenocorticotropic hormone deficiency (3); adenocarcinoma (2); bacterial infection (2); breast tumors (2); Hepatitis (2); lupus (2); lymphedema (2); viral diseases (2); X-linked agammaglobulinemia (2); acute myeloid leukemia (1); Adrenal insufficiency (1); ankylosing spondylitis (1); autoimmune enteropathy (1); autoimmune hemolytic anemia (1); B-Cell CLL (1); Brain atrophy (1); carcinoid (1); Chronic colitis (1); chronic kidney disease stage 2 (1); Cirrhosis (1); cocaine use disorder (1); colon adenocarcinoma (1); combined immunodeficiency (1); endocrinopathies (1); epilepsy (1); experimental autoimmune encephalomyelitis (1); familial Mediterranean fever (1); Fanconi anemia (1); gastric atrophy (1).
A further 44 diseases each share a sentence with NFKB2 in 1 paper.